IL27 (interleukin 27)
Diseases named in the same sentence as IL27 in open-access papers (continued):
Sharing a sentence is not in itself a finding about the gene and the disease.
viral infection (continued). "The availability of IL-27, the cell types responding and the kinetics of virus infection all may come into play to determine whether IL-27 signaling enhances or attenuates antiviral immune responses." (PMID 35634328, 2022). "The aspect that appears critical to whether the IL-27-induced IL-10 response attenuates or augments viral infection is timing." (PMID 35634328, 2022). "The timing of IL-27 function during virus infection appears paradoxical, as early IL-27 signaling is important for enhancing innate antiviral responses and potentially regulating IFNγ production, but also may attenuate these very responses by increasing IL-10." (PMID 35634328, 2022). "It is interesting to speculate whether IL-27 has a dominant role in the induction IFNs in general during viral infection." (PMID 35634328, 2022). "IL-27 was shown to support the development of pDCs in mice during viral infection." (PMID 35634328, 2022). "The timing of IL-27 activity may be critical as to whether it increases or decreases IFNγ production systemically during viral infection." (PMID 35634328, 2022). "There are mixed reports as to whether IL-27-induced IL-10 increases or decreases survival following viral infection." (PMID 35634328, 2022). "STAT1/STAT3 heterodimerization is favoured by IL-27 during viral infections such as HBV and HSV, and may represent an alternative pathway to ISG production, as the STAT1/STAT3 heterodimer is not typically associated with IFN signaling." (PMID 35634328, 2022). "Additionally, IL-27 can directly interfere with viral infection both by acting similarly to an IFN itself and by modulating the differentiation and function of various immune cells." (PMID 35634328, 2022). "Blockage of IL-27 in septic patients leads to reduced mortality and bacterial burden, indicating that modulation of IL-27 may be helpful in infections, but studies regarding psoriasis and viral infections are still scarce." (PMID 34068473, 2021). "Notably, the mechanism by which IL-27 regulates NK cell effector functions during viral infections is yet to be fully understood." (PMID 34440725, 2021). "IL-27 was reported to have antiviral and anti-inflammatory effects in viral infection." (PMID 33381596, 2020). "IL-27 also elicits pleiotropic effects during viral infection." (PMID 32802395, 2020). "Notably, the mechanism by which IL-27 regulate NK cells effector functions during viral infections is yet to be fully understood." (PMID 30899058, 2019). "Systemic viral infection rapidly induces IL-27 upregulation." (PMID 29593047, 2018). "In addition, our results suggest a novel DC positive-feedback loop, in which viral infection rapidly promotes production of DC- and macrophage-derived IL-27, directly promoting pDC accumulation and enhancing IFN-I transcription in cDCs early after infection." (PMID 29593047, 2018). "Given this highly context dependent role of IL-27 in viral infection, we questioned its function in the immune response to persistent/latent viruses that, after a prolonged period of site-restricted viral replication, establish lifelong latency to subvert immune clearance." (PMID 30044874, 2018). "Thus IL-27’s impact on controlling viral infection seems to extend beyond its downstream mediator IL-10." (PMID 30044874, 2018). "Further studies are necessary to clarify which BM cells produce IL-27 during malaria infection; mesenchymal stromal cells might be a candidate because of their reported IL-6 production during viral infection, as described in the next section." (PMID 26991425, 2016). "Although IL-27 acts to induce IL-10 during primary virus infection, CD8+ T cells have a loss of responsiveness to IL-27 during recall response related to an attenuation of the glycoprotein 130 cytokine receptor, resulting in down-regulation of IL-10 production." (PMID 25651926, 2015).
viral infection (continued). "The induction of pro-inflammatory cytokines such as COX-2, TNF, IFNs, IL27 and CXCL10 is essential for the host immune response during virus infection, but inappropriately sustained induction causes cytokine-storms, which are associated with a wide variety of infectious diseases." (PMID 24138989, 2013). "Given the importance of IL-6, TNF-α, IL-12p40, and IL-27 in aiding the immune system during viral infections such as influenza, vaccinia virus, HIV, and herpes simplex and supporting viral immunity, a fermentate that can enhance these cytokines could be beneficial." (PMID 38674902, 2024). "In addition, it has been described that miRNAs can be induced by the IL-27 pathway during viral infections; therefore, it would be important to investigate whether this miRNA may be being induced by the IL-27 pathway and promoting an inflammatory response." (PMID 39637135, 2024). "Interestingly, the dualities of IL-27 and -35 are evidently shown in the course of virus infections; they regulate the synthesis of cytokines and antiviral molecules, proliferation of T cells, and viral antigen presentation in order to maximize virus clearance by the host immune system." (PMID 37108513, 2023). "However, IL-27 significantly augmented NKG2D activation of NK cells and subsequent IFNγ production, suggesting that IL-27 may act as an additional signal alongside IL-15 or IL-18 to enhance NK cell activation at the site of viral infection." (PMID 35634328, 2022). "However, as numerous stimulants promote IFN and IL-27 production during viral infection, such as viral PAMPs, DAMPs, and other cytokines, the role of IL-27 in promoting IFN production may be supportive, rather than dominant." (PMID 35634328, 2022). "Thus, it is possible that during acute viral infection, neutrophils and monocytes/macrophages may provide the ‘third signal’ to NK cells at the site of infection through the production of IL-27." (PMID 34440725, 2021). "Thus, it is possible that during an acute viral infection, neutrophils and monocytes/macrophages may provide the ‘third’ signal to NK cells at the site of infection through the production of IL-27." (PMID 30899058, 2019). "The marked increase in cytokines such as IL-27, IFN-γ, and TNF-α indicates robust immune activation, which is crucial for combating viral infections." (PMID 41189879, 2025). "In response to viral infections, the host induces an antiviral response characterized by the production of type I interferons (IFN-α, IFN-β), type III interferons (IFN-λ), and IL-27 (IFN-V)." (PMID 40711072, 2025). "When targeting the fowl plaque virus infection, STAT-1 signalling was initiated by IL-27 in order to elevate the expression of antiviral products to reduce the viral load in infected birds." (PMID 37108513, 2023). "Type I IFN signaling was reported to enhance IL-27 secretion by myeloid cell populations during MCMV and IAV viral infections, which in turn promoted IL-10 production by T cells in vivo." (PMID 35634328, 2022). "Previously, the anti-inflammatory role of IL-27, through effective production of IFN-γ was studied for prevention of viral infections such as HBV, HCV and HCV/HIV co-infection." (PMID 34996392, 2022). "Clinical studies demonstrate that IL-27 and IFN levels are tightly correlated during viral infection." (PMID 35634328, 2022). "There is increasing evidence that IL-27 is a potent inducer of IL-10 production from CD4+ and CD8+ T cells in a variety of viral infections, thereby having implications on antiviral immune responses and viral clearance." (PMID 35634328, 2022). "Our results further support that IL-27 may serve as a therapeutic agent in cytokine-based therapy for the treatment of HIV and other viral infections." (PMID 40129989, 2025). "IL-27 treatment induces multiple interferon-stimulated genes (ISGs) in macrophages and regulates the expression of multiple host factors, which are involved in HIV replication and other viral infections." (PMID 40129989, 2025).
viral infection (continued). "We observed that IL-27 regulates ZIKV infection in human trophoblasts in vitro, therefore we next sought to determine how placental IL-27 signaling influences pregnancy outcomes during broad inflammation and viral infection in vivo." (PMID 40502752, 2025). "The role of IL-27 in the setting of viral infections is not well defined and both pro-inflammatory and anti-inflammatory functions have been described." (PMID 38966644, 2024). "Unlike bacterial-induced outcomes, but more similar to those of parasites, the harmful effects of viral infections are amplified in the absence of IL-27 signaling." (PMID 32802395, 2020). "This suggests that IFN-III and IL-27 could be considered new therapeutic alternatives to help control viral infections without triggering an exacerbated inflammatory response in patients." (PMID 38720890, 2024). "Since we and others have reported that IL27 induces a strong response to viral infections in an IFN-independent manner, in the present study we investigated transcription levels of IL27 in COVID-19 patients to determine whether IL27 might induce an antiviral response to SARS-CoV-2 infection." (PMID 37310504, 2023). "In addition, although the absence of IL-27 consistently reduces IL-10 producing CD4 T cells in multiple types of viral infections, the outcome for viral control is highly variable." (PMID 30044874, 2018). "However, a direct connection between IL-27, macrophage polarization, IFN production, and viral infection has not yet been studied in detail." (PMID 35634328, 2022).
colitis (42 papers, 2011 to 2025). Inflammation of the colon. "In the colon, Cui and colleagues demonstrated a protective role for IL-27 in a colitis-associated colorectal cancer murine model using an IL-27 Rα knockout model." (PMID 35336801, 2022). "IL-27 signals were required for IFN-γ production during DSS colitis, while loss of Il27ra resulted in a transient defect in IFN-γ production in some models infectious models, for example, Leishmania major." (PMID 23554861, 2013). "Moreover, 2,4,6-trinitrobenzenesulfonic acid (TNBS)-treated WT mice showed acute, severe, left-sided colitis, whereas delivering Lactococcus lactis-expressing IL-27 (LL-IL-27) inhibited TNBS-induced colitis and weight loss." (PMID 38566992, 2024). "FFAR2 deficient dendritic cells lead to exacerbated colitis by controlling excessive IL-27." (PMID 34572293, 2021). "However, IL-27 plays a context-dependent role in inflammation: in the gut, Treg-derived IL-27 can limit Th17 responses and ameliorate colitis, whereas in other tissues such as the CNS or joints, IL-27 may exert pro-inflammatory effects by promoting pathogenic Th1 or Tr1 responses." (PMID 40933988, 2025). "IL-27 promotes inflammation in diseases such as crescentic glomerulonephritis, colitis, and systemic sclerosis, but IL-27 suppresses inflammation in diseases such as autoimmune arthritis, allergic asthma, and autoimmune encephalomyelitis." (PMID 38786961, 2024). "A possible therapeutic method for the treatment of colitis known as LL-IL-27, IL27, which is actively generated in situ by the food-grade bacteria Lactococcuslactis, has been proposed by some studies." (PMID 39766196, 2024). "In a rat model of colitis, curcumin was shown to decrease disease activity, with reduced colonic mucosa damage, through the decreased expression of IL-27 via inhibition of the TLR4/NF-κB signalling pathway." (PMID 39123583, 2024). "It has been recently demonstrated that CD74 expression in IEC is crucial for inflammation-induced mucosal healing in different murine colitis models, further supporting a protective role of IL-27 in IEC as previously demonstrated by us." (PMID 37818353, 2023). "IL-27, a pleiotropic cytokine belonging to the IL-12 family, has immunosuppressive and therapeutic effects in colitis." (PMID 37049407, 2023). "In animal model, treatment with IL-27 attenuates experimental colitis through the suppression of the development of IL-17-producing T helper cells." (PMID 35082553, 2022). "IL-27-producing L. lactis proved to be more effective than the administration of either IL-10-secreting L. lactis or IL-27 alone in resolving colitis in a preclinical mouse model." (PMID 35628274, 2022). "This study went further to show that IL-27 treatment also reduced disease activity in dextran sulfate sodium- (DSS-) induced colitis model in mice." (PMID 35082553, 2022). "A previous animal study showed that IL-27 is involved in the immunopathology of TNBS-induced colitis in rats via the TLR4/NF-κB signaling pathway." (PMID 34744512, 2021). "In this stage of colitis, food intake with βGh (CβGh+ group) up-regulated the expression of the Il13, Il21, Il27, and Lta genes and down-regulated the expression of the Il1a, Il11, and Il17a genes." (PMID 33923129, 2021). "Our previous study has shown that interleukin-27 (IL-27)/IL-27 receptor signaling provides protection against C. difficile-induced colitis in AAD patients." (PMID 32293302, 2020). "IL-27 producing L. lactis proved more effective than both its IL-10 producing counterpart and systemic administration of IL-27 in colitis mouse models." (PMID 32296696, 2020). "A significant up-regulation of genes encoding the following cytokines and their receptors—Il13, Il16, Il27, Il2rb, Il2rg, Il6r Il10ra, Faslg, Ltb, Osm, Spp1, Tnf, Tnfsf14—was noted in animals with colitis (CβG−)." (PMID 31590413, 2019).
colitis (continued). "Instead, as found in T. gondii infection, collagen induced arthritis and cell-induced colitis, IL-27 promotes the activation and proliferation of Tregs, especially in the airways, in murine RSV infection." (PMID 28953978, 2017). "Those that were upregulated by 1 log fold or higher include IL-9, IL-13, IL-4, IL-17A, IL-5, IL-24, IFN-γ, IL-10, IL-11, and IL-27, many of which are known cytokines involved in the pathogenesis of colitis." (PMID 21365015, 2011). "Moreover, there were increased serum levels of IL-27 in Clostridium difficile-induced (CDI) colitis patients as compared to that in healthy controls, and the IL-27 expression in stools from CDI patients was significantly increased." (PMID 38566992, 2024). "On the other end of the spectrum, IL-27 agonism has been explored for its therapeutic use in inflammatory autoimmune dysregulation such as experimental autoimmune encephalomyelitis and colitis." (PMID 35579417, 2022). "Interestingly, engineered IL-27-producing L. lactis proved more effective than both the IL-10 producing counterpart and systemic administration of IL-27 in colitis mouse models." (PMID 35082553, 2022). "For example, in the ATXN2L locus having multiple eQTL/i-rQTL effects for multiple genes, the eQTL effect on IL27 could be responsible for IBD, because the anti-inflammatory roles of IL-27 have been established in a murine colitis model." (PMID 36002455, 2022). "IL-27 is a key coordinator of immune regulation in the respiratory tract and is suggested as a potential rescue therapy for acute severe colitis by attenuation of colonic mucosal innate immune response." (PMID 35334059, 2022). "Treatment with IL-27 attenuates experimental colitis through the suppression of the development of IL-17-producing T helper cells in TNBS-induced colitis model even after active colitis was established." (PMID 35082553, 2022). "In both experiments, clinical score of colitis was reduced in the IL-27-treated B27-rats." (PMID 36818477, 2022). "Oral delivery of IL-27 recombinant bacteria can ameliorate T cell transfer-induced colitis in mice whilst a T. muris infection in an IL-10/IL-27 KO mouse leads to less severe pathology than seen in the IL-10 KO control due to a decreased pro-inflammatory profile." (PMID 34078488, 2021). "Consistent with murine studies, human dendritic cells exposed to R110 showed exquisite differential gene regulation, including IL-27 transcription, suggesting a shared mechanism between the two species, hence positioning R110 as potentially effective at treating colitis in humans." (PMID 34572293, 2021). "It was also shown that the alterations in both IL-35 and IL-27 exacerbate T cell transfer colitis." (PMID 33042131, 2020). "IL-27 has also been shown to inhibit the TGFβ-mediated induction of Treg cells, and adoptive transfer of Il27ra−/− Treg cells into lymphopenic mice resulted in attenuated colitis, which was attributed to increased induction of peripheral Treg cells." (PMID 31379810, 2019). "IL-27 might mediate this effect by inhibiting cell death, similar to what has been shown in a colitis model and as we reported for CD4 T cells deficient in the IL-27 co-receptor gp130 during chronic LCMV infection." (PMID 30044874, 2018). "Oral delivery of recombinant IL-27 food-grade bacterium Lactococcus lactis ameliorates the murine colitis in a T cell-dependent colitis model, including improving survival, decreasing clinical score and pathologic score, downregulating inflammatory cytokines, and increasing IL-10." (PMID 28420941, 2017). "Furthermore, the pro-inflammatory properties of IL27 in the skin sync well with its ability to exacerbate other inflammatory diseases such as colitis and arthritis." (PMID 27738312, 2016). "However, IL-10−/−IL-27rα−/− mice had mild crypt elongation and reduced expression of the pro-inflammatory cytokines, suggesting that IL-27 may promote colitis development." (PMID 38566992, 2024).
colitis (continued). "This may indicate that IL-27 would be particularly effective in disease flare and may reduce the need for use of steroid therapy or be exploited as a colon rescue therapy to avoid colectomy in acute severe colitis." (PMID 35336801, 2022). "With respect to the differences in the role of IL-27 in colitis, the reasons may correlate with following: For instance, it is unclear that IL-27 plays a pro-inflammatory or an anti-inflammatory role in different immune cells, and then contributes to colitis or inhibits colitis." (PMID 38566992, 2024). "All the findings discussed the role of LL-IL-27, AAV-IL-27, scIL-27, and anti-IL-27 antibodies in colitis and demonstrated that IL-27 inhibits colitis by suppressing Th17-mediated immune responses." (PMID 38566992, 2024). "For IL-27 promoting colitis, a study found that IL-27-mediated stimulation of non-T cells (especially macrophages and DCs) was a risk for intestinal inflammation." (PMID 38566992, 2024). "Mucosal delivery of the immunosuppressive cytokine, such as IL27, IL35, can reduce colitis." (PMID 36814913, 2023). "In line with this, we previously found that pre-treatment of mice with orally delivered IL-27 prior to onset of TNBS mediated colitis did not alter disease induction." (PMID 35336801, 2022). "Previous works demonstrated either a crucial role of IL-10 for the anti-inflammatory effect of IL-27 in a model of colitis or that IL-10 was not required for the suppression of Th17 cells in the context of experimental autoimmune encephalomyelitis." (PMID 36818477, 2022). "Whether the expression of LAG-3 on Tr1 cells is functionally important has not been determined, but it was recently shown that IL-27 induced expression of LAG-3 on Foxp3+ Treg cells had suppressive functions in a colitis model in mice." (PMID 26866695, 2016). "Our data also suggest changes in cytokine receptor gene expression on MulTreg, which may include a shift from IL-10 and IL-27 induced regulatory function towards enhanced TGFBR1 signaling which has been shown to induce Treg retention in inflamed sites and control of experimental colitis." (PMID 34539651, 2021).